THBS2 (thrombospondin 2)
Diseases named in the same sentence as THBS2 in open-access papers (continued):
Sharing a sentence is not in itself a finding about the gene and the disease.
lung cancer (24 papers, 2016 to 2026). A malignant neoplasm involving the lung. "Additionally, previous evidence revealed the promise of THBS2 as a candidate diagnostic biomarker for early-stage lung cancer." (PMID 35547750, 2022). "It has been shown that the downregulation of THBS2 is closely related to adverse survival in non‐small cell lung cancer, lung adenocarcinoma, and liver cancer." (PMID 35789544, 2023). "For example, circular RNA circ_0020123 regulates THBS2 through sponge miR‐590‐5p to facilitate non‐small cell lung cancer cell proliferation and migration and suppress cell apoptosis." (PMID 35879877, 2023). "It has been reported that THBS2 is a prognostic biomarker, either poor or good, in a variety of human cancers, including lung cancer 67-69." (PMID 35547750, 2022). "THBS1 was in general underexpressed in lung cancer; in contrast, mRNA levels of THBS2 were markedly overexpressed in a number of datasets of non-small cell lung carcinoma (NSCLC), including lung adenocarcinoma (AC) and squamous cell carcinoma." (PMID 27513329, 2016). "We next focused on investigating the changes in THBS1 and THBS2 mRNA expression in lung cancer subtypes." (PMID 27513329, 2016). "The findings of the present study can shed light on the specific role of THBS2 in the development and progression of lung cancer and clinical outcomes." (PMID 27513329, 2016). "Second, along the same line, mining two independent datasets that contain lung cancer (GSE135222) or melanoma (GSE78220) patients treated with anti-PD1/PD-L1 immunotherapies, we observed that higher THBS2 expression was associated with poor response and short PFS/OS after immunotherapy." (PMID 35547750, 2022). "In contrast, thrombospondin-2 expression by lung cancer cells promotes lung cancer bone metastasis through osteoclastogenesis which may explain the association of this isoform with recurrence in adenocarcinoma." (PMID 33014869, 2020). "However, it is also found that THBS2 was able to promote tumor metastasis by inducing matrix metalloproteinase-13 production in lung cancer cells." (PMID 31296790, 2019). "COL5A2, MXRA5, and VCAN coexpressed with THBS2 may have significant oncogenic functions in both breast and lung cancers." (PMID 27513329, 2016). "The increase in THBS2 levels in lung cancer tissue may be viewed as resistant to THBS2-induced anti-angiogenic effect in the subtype of lung AC." (PMID 27513329, 2016). "However, the expression pattern of THBS1 and THBS2 is different, and the specific role of THBS2 in different subtypes of lung cancer remains largely unclear." (PMID 27513329, 2016). "THBS2 may also play a significant role in the detection of colon cancer, lung cancer, and GC." (PMID 38737262, 2024). "Markedly over-expression of THBS2 and its co-expressed genes (such as VCAN, CLO11A1, FAP) predicts poor survival of patients with lung cancer; down-regulation of VCAN and THBS2 inhibits cell proliferation in NSCLC." (PMID 28881680, 2017). "Thrombospondin 2 (THBS2) stimulates osteoclastogenesis in a receptor activator of nuclear factor kappa-Β ligand (RANKL) dependent way, promoting osteolytic lesions in lung cancer-derived bone metastasis." (PMID 35159353, 2022). "Previous reporters have shown that THBS2 could regulate MMP-2 and MMP-13 to promote tumor metastasis of prostate cancer and lung cancer." (PMID 36118676, 2022). "As anti‐TNC antibody‐functionalized nanopillars enrich cancer‐associated sEVs, we expected DECODE to provide an sEV molecular profile with higher expressions of CD63, THBS2, VCAN, and TNC in the three lung cancer cell lines and low/negligible biomarker expression from HBECs and PBS controls." (PMID 36394090, 2022).
lung cancer (continued). "The survival rates of AC lung cancer patients with high THBS2 expression were significantly worse both in the never-smoked (HR = 3.37) and ever-smoked (HR = 1.88) groups." (PMID 27513329, 2016). "In vitro transwell migration assays showed that the presence of THBS2 (50 ng/mL, the average level in the serum of patients with early-stage lung cancer 64) dramatically facilitated the migration of LUAD cells, although THBS2 does not promote their proliferation." (PMID 35547750, 2022).
ovarian carcinoma (24 papers, 2013 to 2025). A malignant neoplasm originating from the surface ovarian epithelium. "Frequent point mutations of the THBS2 gene mainly occurred near sequence 1-200 (ovarian cancer cell lines: E82A and G107E; cBioPortal database: R189P, T99M, X18_ splice)." (PMID 37024829, 2023). "High expression of THBS2 is associated with an increased risk of hematogenous and lymphatic metastasis in ovarian cancer." (PMID 37024829, 2023). "This indicates that CCDC170, COL14A1 and THBS2 are expected to become targets for the diagnosis and treatment of ovarian cancer." (PMID 37024829, 2023). "Mone 1062—one of the mones in the identified cluster—was additionally highly correlated with ECM2, THBS1 and THBS2, which have been suggested to play a significant role in ovarian cancer drug resistance and metastasis." (PMID 35676395, 2022). "In ovarian cancer, THBS2 mRNA expression has been shown to be upregulated in more aggressive tumors (malignant compared with borderline), advanced stage, and high grade." (PMID 36222710, 2022). "Second, signatures increased in collagen expression together with LOX, THBS2, TIMP3 and SPARC have also been associated with decreased survival in ovarian cancer." (PMID 33379263, 2020). "Other genes such as FAP, CTSK, FBN1, THBS2, SPARC, and COL1A1 are also known to be ovarian cancer associated." (PMID 27843486, 2016). "In addition, the results of our Kaplan-Meier analysis showed that high expression of THBS2 significantly affected overall survival in patients with ovarian cancer (p < 0.001)." (PMID 37024829, 2023). "In addition, the expression of COL14A1 and THBS2 was significantly increased in ovarian cancer cell lines compared to normal ovarian cells (P < 0.05, P < 0.01), but the differential expression in CCDC170 was the opposite." (PMID 37024829, 2023). "A treatment that combines engineered CAR-T cells targeting CD47 and inhibits secreted THBS2/THBS3 using antibodies may constitute a valuable therapeutic strategy to inhibit ovarian cancer progression." (PMID 36352420, 2022). "THBS2 mediates cell-to-cell and cell-to-matrix interactions and may function as either a potent inhibitor of tumor growth and angiogenesis in ovarian carcinoma." (PMID 29190912, 2017). "THBS2 hypermethylation might be responsible for altered expression of thrombospondin-2 protein in ovarian cancer and endometrial adenocarcinomas." (PMID 26482433, 2015). "THBS2 also has CpG island methylation in malignant ovarian tumors." (PMID 26035298, 2015). "In particular, THBS2, COL1A1, and COL5A1 genes are upregulated in most cancer types, except for bladder, kidney, melanoma, and ovarian cancer." (PMID 40860666, 2025). "Among them, the THBS2 and COL14A1 genes had the most significant effect on the overall survival of ovarian cancer patients." (PMID 37024829, 2023). "We verified the expression of CCDC170, THBS2 and COL14A1 in ovarian cancer cells by Western blotting (WB) and immunofluorescence assay (IF)." (PMID 37024829, 2023). "In addition, we also used TCGA data to detect the expression of COL14A1, THBS2 and CCDC170 genes in different stages of ovarian cancer patients." (PMID 37024829, 2023). "Similarly, although THBS2 and COL14A1 also showed differential expression in ovarian cancer cell lines and normal ovarian cells, the results were not as significant as those for CCDC170." (PMID 37024829, 2023). "Similar to the mesenchymal subtype from the original TCGA study of ovarian cancer, S‐ECM shows upregulation of genes such as COL5A2, COL1A1, COL3A1, THBS2, COL11A1, COL6A3, and MMP2 that are involved in epithelial‐to‐mesenchymal transformation (EMT) processes, metastasis, and chemoresistance." (PMID 36637997, 2023). "Thrombospondin 2 mediates cell-to-cell and cell-to-matrix interactions and may function as either a potent inhibitor or stimulator of tumor growth and angiogenesis in ovarian carcinoma, although no studies evaluated thrombospondin 2 according to ovarian histological type." (PMID 24175302, 2013).
colon cancer (22 papers, 1999 to 2024). "The high expression of THBS2 promotes the metastasis of colon cancer and is associated with an advanced clinical stage." (PMID 35186032, 2022). "Our findings indicate that pan-dCAFs are a major source of TSPs in the colon cancer microenvironment, and THBS2 may be linked to the CAFs differentiation and increased pro-cancer activity." (PMID 38827236, 2024). "It is suggested that these hallmark genes (BGN, THBS2) may not only be novel EMT indicators but also provide direction for several clinical medications utilized in colon cancer treatment." (PMID 36377223, 2022). "Moreover, the overexpression of THBS2 is associated with shorter disease-free survival (DFS) in colon cancer." (PMID 34804159, 2021). "Compared with these results, our study revealed that THBS2 had the potential to be used as prognostic biomarker for colon cancer metastasis and clinical treatment." (PMID 36377223, 2022). "It is thought that BGN and THBS2 overexpression contributes to the abnormality of colon cancer cells." (PMID 36377223, 2022). "The most significant signatures associated with colon cancer metastasis were determined to be BGN and THBS2." (PMID 36377223, 2022). "The expression level of THBS2 in colon cancer was significantly increased, and the higher the expression level of THBS2, the worse the OS of patients." (PMID 35186032, 2022). "IHC staining results indicated that BGN and THBS2 were significantly up‐regulated in most of the colon cancer tissues than health adjacent tissues." (PMID 36377223, 2022). "In the future, it is necessary and logical to investigate the function and mechanism of these potential signature genes (BGN and THBS2) for colon cancer metastasis using an experimental animal model and patients derived tumour cells." (PMID 36377223, 2022). "Eight significantly over‐expression genes in tumour tissues (BGN, THBS2, SPARC, CDH11, MFAP2, MMP11, SPP1 and THY1) were defined as significantly signature genes that implicated in colon cancer metastasis progress." (PMID 36377223, 2022). "It is suggested that BGN and THBS2 were critical in promoting colon cancer cells proliferation and tumourigenicity, and influent the migration and invasion of colon cancer cells during cancer metastasis." (PMID 36377223, 2022). "In the present study, we found that THBS2 was overexpressed in both primary colon tumor and liver metastases." (PMID 28424419, 2017). "Recently, in vivo studies have shown that colon cancer metastasis results from an alteration in the balance between the angiogenesis inhibitor thrombospondin-2 and the angiogenic growth factor VEGF189." (PMID 12189553, 2002). "Additionally, this study found that THBS2 affects CAFs differentiation and function solely in colon cancer; future research will further explore this molecule's role across various cancers." (PMID 38827236, 2024). "It has also been reported that THBS2 may be a serum biomarker in the diagnosis of colon cancer and lung cancer." (PMID 35186032, 2022). "BGN and THBS2 knockdown significantly reduced colon cancer cells migration and invasion, as well as down‐regulating three EMT‐related proteins (Snail, Vimentin and N‐cadherin), and increasing the proliferation inhibitory effect of 5‐fluorouracil, irinotecan and oxaliplatin treatment." (PMID 36377223, 2022). "It is strongly suggested that decreased expression of these genes (BGN, THBS2) could block the dominant signalling molecules in colon cancer metastasis." (PMID 36377223, 2022). "Therefore, we speculate that the high expression of THBS2 and COMP in colon cancer may be associated with CAFs phenotype conversion." (PMID 38827236, 2024). "Furthermore, the hall markers of BGN and THBS2 were intensively validated findings for key regulators candidate of colon cancer metastasis using knockdown and cellular functions assay and evaluated the synergic effect of treatment combined with 5‐Fluorouracil (5‐FU) first‐line clinical drugs." (PMID 36377223, 2022).
colon cancer (continued). "First, we observed significant upregulation of THBS2 and COMP in colon cancer, both of which displayed significant prognostic value." (PMID 38827236, 2024). "Studies in colon cancer cell lines, such as CT26 and LoVo, have shown that overexpression of THBS2 enhances cellular glycolysis and lactate production, facilitates M2 polarization of macrophages, blocks T-cell proliferation, and reduces T-cell cytotoxicity." (PMID 38827236, 2024). "It is also proposed the potential action model of BGN and THBS2 regulating EMT and metastasis processes in colon cancer cells." (PMID 36377223, 2022). "Five genes (BGN, THBS2, SPARC, CDH11 and SPP1) were initially identified as potential biomarkers and therapeutic targets of colon cancer metastasis." (PMID 36377223, 2022). "Correlation analyses using TCGA data showed that THBS2 is significantly positively correlated with THBS1, THBS3, THBS4, and THBS5 in colon cancer." (PMID 34804159, 2021). "Furthermore, the spatial co-localization of CAFs marker genes with THBS2, THBS4, and COMP in colon cancer supports these findings." (PMID 38827236, 2024). "On the one hand, it is reported that THBS2 plays protective roles in the tumorigenesis of many cancers and its expression is inversely correlated with vascularity of glioma, skin cancer, NSCLC, and colon cancer." (PMID 31296790, 2019). "Among the upregulated stromal cell-enriched proteins, some proteins have been reported to be potential markers in colon cancer prognosis or tumorigenicity, such as collagen XII (COL12A1), thrombospondin 2 (THBS2), collagen triple helix repeat-containing protein 1 (CTHRC1) and COL5A2." (PMID 26338966, 2015). "However, TSP2 is also produced by non-skeletal cells, such as trophoblasts and colon cancer cells, where the THBS2 gene is expressed and regulated by miRNAs." (PMID 35008515, 2021). "A subset of ECM glycoproteins, such as thrombospondin-2 (THBS2), ECM regulators including lysyl oxidase homolog 2 (LOXL2) or procollagen-lysine,2-oxoglutarate 5-dioxygenase 1 (PLOD1), and affiliated proteins such as MUC13 have been specifically identified in colon cancer samples." (PMID 33297478, 2020).
breast carcinoma (19 papers, 2011 to 2025). "The survival analysis indicated that increased THBS2 expression levels were associated with poor survival rates in breast cancer." (PMID 27513329, 2016). "In contrast, the survival analysis indicated that overexpression of THBS2 in breast cancer was associated with a poor prognosis." (PMID 27513329, 2016). "COL12A1 and THBS2 are components of extracellular matrix (ECM) proteins that significantly upregulate in breast cancer compared with normal breast tissue." (PMID 39954675, 2025). "Another investigation of breast cancer determined that inhibiting tumor cell interactions with THBS-2 reduced tumor growth and metastasis to lymph nodes and the lungs, further supporting an important role for THBS-2 in breast cancer progression." (PMID 30154546, 2018). "N-terminal recombinant fragment of THBS2 inhibited breast cancer growth and metastasis by CD36 mediated activation of endothelial cell apoptosis." (PMID 29190912, 2017). "In support of this hypothesis, in breast cancer, THBS2 was found to promote cell invasion by activating the PI3K/AKT signaling pathway, while THBS1-induced breast cancer cell invasion occurs by the YAP/FAK and transforming growth factor (TGF)-beta/Smad3 axes." (PMID 38339060, 2024). "Additionally, CEBPB regulates breast cancer cell migration and invasion through diverse pathways, including THBS2 suppression, the PAK4–CEBPB–CLDN4 axis and the cAMP/AMPK/CEBPB axis." (PMID 38982317, 2024). "Genes coexpressed with THBS2 in breast cancer were examined." (PMID 27513329, 2016). "Del-Pozo-Martin and colleagues have recently demonstrated that in the first phase of metastatic niche induction in breast cancer, AXL+ MICs activate fibroblasts by thrombospondin 2 (THBS2) release." (PMID 30927908, 2019). "Thrombospondin 2 (THBS2), for example, a mesenchymal state-dependent tumor secreted ECM molecule promoted stromal niche activation via integrin-mediated signaling in the early phase of colonization of metastasis-initiating breast cancer cells." (PMID 35737114, 2022).